DES (desmin)
Diseases named in the same sentence as DES in open-access papers (continued):
Sharing a sentence is not in itself a finding about the gene and the disease.
tumor (continued). "Immunohistochemical staining demonstrated positive expression of Desmin, Myogenic Differentiation 1 (MyoD1), and Myogenin in the tumor cells, with a Ki-67 proliferation index of 70%, while were negative for CD20, cytokeratin (CK), CD79a, CD38, and chromogranin A (CgA)." (PMID 40520793, 2025). "Focal, weak positivity for desmin was detected in the tumor cell cytoplasm." (PMID 40226945, 2025). "Moreover, we confirmed via double staining that myostatin and desmin/SMA were expressed in the same tumor in an almost mutually exclusive pattern, even when myogenic markers were only focally expressed." (PMID 40868997, 2025). "Tumor cells are strongly positive for Desmin and rarely express CD34 and SMA." (PMID 41137250, 2025). "These tumor cells were positive for Desmin, MyoD1, and Myogenin." (PMID 40040389, 2025). "However, tumor cells often show positivity for vimentin, desmin, smooth muscle actin, CD34 or estrogen, and progesterone receptors." (PMID 39463662, 2024). "A small number of tumour cells were positive for desmin and SMA." (PMID 38151535, 2024). "Indeed, by comparing the tumor core and tumor margin, we showed that cells expressing stromal markers, such as Desmin, Collagen I and αSMA, are mainly located in the periphery of the tumor, surrounding the neoplastic mass." (PMID 38338669, 2024). "The tumor is variably immunoreactive for desmin, SMA, h-caldesmon, and CD10." (PMID 39064514, 2024). "Interestingly, the relative area of the vasculature covered by desmin-positive pericytes was significantly reduced in CD93–/– HCmel12 tumor vessels as compared with wild-type tumor vessels." (PMID 38441970, 2024). "Immunohistochemical staining demonstrated that the tumor cells exhibited partial cytoplasmic positivity for S-100 protein, focal cytoplasmic positivity for cytokeratin (CK), and desmin." (PMID 39612400, 2024). "The tumor cells were variably positive for desmin, myogenin, and MYOD1." (PMID 39439633, 2024). "The mesenchymal component of the tumor may exhibit immunoreactivity to markers such as vimentin, smooth muscle actin, α-1-antitrypsin, and desmin." (PMID 39737275, 2024). "Additionally, the tumor was positive for desmin, myogenin, and MYOD1, suggesting skeletal muscle differentiation." (PMID 39439633, 2024). "The tumor cells were positive for immunohistochemistry markers desmin, MyoD1, and vimentin." (PMID 38500901, 2024). "Immunohistochemically, the tumor was positive for transgelin, desmin, and h-caldesmon." (PMID 37466765, 2024). "Immunohistochemically, the tumor cell showed positivity for desmin, smooth muscle actin and CD10." (PMID 37466765, 2024). "Tumor cells express desmin, h-caldesmon, and SMA; however, their expression may be weak and/or patchy if the tumor is poorly differentiated or myxoid." (PMID 39064514, 2024). "Tumor cells are immunoreactive for desmin and actin, especially the myoid bundles." (PMID 39803071, 2024). "In addition, the tumor cells show strong immunoreactivity for desmin compared with cellular angiofibroma." (PMID 38600580, 2024). "Other immunohistochemical markers that may be focally positive and heterogeneous in tumor cells include desmin, CD68, vimentin, glypican‐3, and CD10, whereas myogenin, S‐100 protein, CD117, and HepPar 1 should be negative." (PMID 39587653, 2024). "Importantly, tumor xenografts revealed a significant reduction in desmin-positive pericytes upon BTK inhibition, indicating a strong reduction in tumor-induced vascularization." (PMID 36612306, 2023). "To verify whether ANV and LbtA5 affect tumor angiogenesis, we assessed the vascular density of B16F10 tumors by immunofluorescence using a rabbit polyclonal antibody against desmin (a tumor vascular marker)." (PMID 36835282, 2023). "Immunohistochemically, tumor cells were positive for MyoD1 and desmin." (PMID 37621777, 2023). "While in this case of ALES, the tumor cells did not express desmin and WT1 and was negative for diagnostic-specific EWSR1-WT1 translocation." (PMID 37518334, 2023).
tumor (continued). "Cytologic analysis demonstrated diffuse sheets of round tumor cells with variable amounts of cohesive eosinophilic cytoplasm and rhabdomyoblasts, and immunohistochemical (IHC) staining for DESMIN, MYOD1, and MYOGENIN consistent with the human solid subtype of ARMS." (PMID 37968277, 2023). "Using IF for CD31 (endothelial cell marker), desmin (perivascular cell markers), and CA-IX (hypoxia marker), we found a site-dependent effect on tumor vasculature and hypoxia in response to CXCR4 inhibition, with statistically significant changes or strong trends only in the metastatic PCa lesions." (PMID 36831366, 2023). "By immunohistochemistry, tumor cells were positive for desmin, estrogen receptor, and CD34." (PMID 37662492, 2023). "Experiments have shown that tumor tissue may express high levels of muscle-specific antigens (troponin and desmin), and there may exist T cells sharing antigens between myocardium and tumor tissue." (PMID 37297017, 2023). "Tumor cells express skeletal muscle markers: desmin, myogenin (Myf4), and/or MyoD1." (PMID 35565289, 2022). "But the tumor cells were only stained positively for Vimentin and had focal expression of Desmin." (PMID 36153506, 2022). "To assess its localization with respect to cells of the tumor vasculature, we applied Z1 to Eml4-Alk lung tissue sections with concurrent staining for both the endothelial marker VE-cadherin and the pericyte marker desmin." (PMID 36192379, 2022). "However, since the tumor cells express desmin and smooth muscle actin, it is believed to originate either from specialized mesenchymal cells or from the multipotent perivascular progenitor cells." (PMID 35177124, 2022). "However, in our case, the co-expression of epithelial membrane antigen, vimentin and desmin by tumor cells strongly supports a diagnosis of DSRCT." (PMID 34996495, 2022). "In addition, for comparative purposes, we also stained orthotopic human tumor models for desmin and myogenin derived from RMS cell lines RD and Rh30 as well as from an institutional RMS patient-derived xenograft (PDX), TCCC-RMS40 (PDX40)." (PMID 35174853, 2022). "The lack of staining-intensity differences for vWF, cytokeratin, and desmin showed that a reduced vascular supply for the tumours through the chorioallantoic membrane was not the cause of cell death." (PMID 33604316, 2021). "The tumor cells typically lack expression of CD1a, CD 68, and Desmin." (PMID 34596165, 2021). "Tumor cell reactivity for cytokeratin, epithelial membrane antigen, and desmin also varies." (PMID 34797454, 2021). "Moreover, Asahina and others suggested that the lesion derived from the intercalated duct cell due to the presence of the tumour cells coexpressing cytokeratin, vimentin, and desmin." (PMID 33712056, 2021). "Tumor cells showed characteristic paranuclear dot-like positive signals for desmin and vimentin." (PMID 34193155, 2021). "Notably, the expression of WT1 and cyclin D1 was also retained in those cases in which the conventional tumor markers (myogenin, desmin and MyoD1 for RMS; CD99 for EWS; NB84 for NB) were focally expressed or more rarely absent." (PMID 34943491, 2021). "Microscopically, the tumor cells were strongly positive for Desmin, Cyclin D1 and WT1, moderately positive for ER/PR, weakly positive for SMA (smooth muscle actin) and negative for CD 10, and the expert pathologist concluded it was “ESS with smooth muscle cells differentiation”." (PMID 32933053, 2020). "Histologically, the tumor showed the typical morphology and immune profile of an epithelioid malignant PEComa, i.e., co-expression of myogenic and melanocytic markers, such as desmin, Melan-A, and HMB45." (PMID 31309284, 2020).
tumor (continued). "Taken together, the peri-tumoral desmin-positive HSCs may be responsible for the production of the fibers that encapsulated and demarcated the tumor tissue." (PMID 32382012, 2020). "In pleomorphic RMS, the tumor cells are positive for desmin, myogenin, and MYOD1." (PMID 32867125, 2020). "In contrast, multivariate analysis of VI evaluated by dual CD31‒desmin immunolabeling showed that poor tumor differentiation (P < 0.001), perineural invasion (P = 0.019), and VI detected by dual immunolabeling (P = 0.009) were independent prognostic factors of worse disease-free survival." (PMID 33253282, 2020). "Immunohistochemically, the tumor cells are positive for desmin, myogenin, and MYOD1." (PMID 32867125, 2020). "Tumor cells were positive for vimentin, ER, PgR, and desmin." (PMID 31240143, 2019). "In our patient, the tumor was positive for desmin, myogenin, and MyoD1." (PMID 29804543, 2018). "Interestingly, examination of tumor-driven vascularization in xenografts revealed a marked reduction of blood vessel density, as determined by reduced immunoreactivity of desmin and von Willebrand Factor VIII (vWF) (data not shown)." (PMID 29100402, 2017). "Some tumor cells also expressed desmin and α-smooth muscle actin." (PMID 28144858, 2017). "Besides ALK, tumor cells stained variably for desmin (4/5), alpha smooth muscle actin (2/5), muscle-specific actin (1/2) and pan-cytokeratin (1/4)." (PMID 27460384, 2016). "Besides ALK, tumor cells also showed variable expression of desmin (4/5), smooth muscle actin (2/5), muscle-specific actin (1/2) and AE1/AE3 (1/5)." (PMID 27460384, 2016). "By immunohistochemistry, tumor cells in 21 of 21 cases were positive for desmin; in 18 of 20 were positive for MYOD1 in a diffuse pattern; in 17 of 19 were positive for myogenin; and in 6 of 11 cases were positive for smooth muscle actin, mostly in a focal pattern." (PMID 27562493, 2016). "To study whether FOXO3 gene-dosage affects blood vessel growth into the tumor, we stained NB15/Ctr and NB15/FOXO3-derived tumors for the expression of the smooth muscle cell marker desmin to identify small vessels within the tumor tissue." (PMID 27769056, 2016). "Tumor cells had positive immunostaining for desmin and smooth muscle actin." (PMID 27759826, 2016). "The tumor stained negatively for desmin, S-100, c-Kit, CK-AE1/AE3, CDK4 and MDM2." (PMID 26337721, 2015). "In past cases, tumor cells showed diffuse and strong positive staining for desmin." (PMID 26208724, 2015). "However, diffuse expression of Desmin in tumor cells have demonstrated in all reported cases, including our presenting case, which is not seen in ALCL." (PMID 26178751, 2015). "Immunohistochemical analysis showed homogeneous positive staining for desmin and mosaic-like expression for Pan-cytokeratin in all examined cell lines including the primary mesothelial cultures, the immortalized cells, and the tumor-derived RN5 cells." (PMID 25877069, 2015). "Subsets of cells (<50% of all tumor cells) expressed terminal muscle differentiation markers such as desmin and actin, and the proliferative index as evidenced by the percentage of Ki67-expressing nuclei was 41.6 ± 12.5% (range 30.5–59.3%; four tumors evaluated)." (PMID 25759794, 2015). "The tumour cells consistently exhibit coexpression of desmin and CD34." (PMID 26187500, 2015). "Moreover, double immunostaining with the endothelial marker CD31 showed colocalization with desmin staining indicating that Netrin-4 enhanced the recruitment of perivascular cells on tumor EC." (PMID 24472220, 2014). "Interestingly, HX170c subcutaneous mouse xenografts regained desmin positivity and also appeared histologically similar to the initial tumor biopsy." (PMID 23882450, 2013). "Occasionally, the tumour has some positive staining with antibodies against desmin." (PMID 23424592, 2013).
tumor (continued). "However, a tumor vascular maturation defined by perivascular desmin+/SMA+ cells coverage was clearly observed along with an increase in endothelial, zonula occludens (ZO)-1 positive, intercellular junctions." (PMID 24391887, 2013). "The tumor cells were strongly positive for Vimentin, Desmin and MyoD1." (PMID 23379991, 2013). "As these neoplasias were composed almost entirely of nLacZ-positive cells (data not shown), the neoplasias were highly invasive and positive for the myogenic markers α-smooth muscle actin and desmin." (PMID 24349213, 2013). "In addition, the neoplasms display varied expression of desmin (89%, 8/9), CD30 (71%, 5/7), SMA (50%, 4/8), and cytokeratin (25%, 2/8), while EMA, S100, CD117, Myf4, myogenin, caldesmin, and HMB45 expression is consistently negative." (PMID 24034896, 2013). "Finally, vessels from ASP13 tumours were surrounded by mural cells that stained positive for α-Smooth Muscle Actin and Desmin proteins, while mural cells were scarce around CYS12 tortuous vessels." (PMID 23506169, 2013). "Also, ASP13 tumours vessels are covered with α-Sma(+)/Desmin(+) cells further highlighting the contribution of VEGF-A to vessel maturation and tumour growth." (PMID 23506169, 2013). "Increased tumor angiogenesis in morphine-treated mice was accompanied by increased vessel-associated desmin-expressing pericytes, but not α-SMA-expressing pericytes." (PMID 22315595, 2012). "Immunohistochemically, the tumour cells were positive for vimentin, actin, desmin, and myoglobin." (PMID 22792486, 2012). "In immunohsitochemical staining the tumour cells were positive for vimentin, desmin, actin." (PMID 23044187, 2012). "In conclusion, desmin staining, identifying pericyte coverage and extent of mature tumor vasculature, may thus be worthy of further investigation as a biomarker to predict the efficacy of anti-angiogenic cancer therapy." (PMID 22141345, 2011). "The human desmin gene is the third on the list, and it was found to be down-regulated in tumor." (PMID 15469618, 2004). "However, desmin-positive striated muscle fibers were intermingled within the tumor." (PMID 41230282, 2025). "Moreover, antibodies directed against α-SMA actin, myosin, and desmin are commonly included to discriminate among mesenchymal tumours deriving from smooth and skeletal muscles while antibodies for Von Willebrand factor are used to recognize haemangioma/haemangiosarcomas." (PMID 37525233, 2023). "Histologically, the ASPcKOP7cKO tumor cells stained sporadically for DESMIN but were no longer positive for RMS diagnostic markers MYOD1 and MYOGENIN; this was specific for ASPcKOP7cKO tumors as ASPcHetP7cKO and ASPcKOP7cHet tumors were still myogenic, small round blue tumors consistent with RMS." (PMID 34535684, 2021). "Compared with NE-4C cells, the tumor showed a general tendency of upregulation of a series of genes representing neural stemness, genes representing neuronal differentiation, and genes representing mesodermal (Acta2, T, Desmin, Kdr) and endodermal tissue (Afp, Foxa2) differentiation." (PMID 33468253, 2021). "Similarly there is a case report of a young dog with eyelid enlargement (lachrymal gland protrusion) and multiple masses throughout the body, for which a diagnosis of ERMS was confirmed with immunohistochemical positivity of the tumour cells for desmin, myogenin and Myo-D1." (PMID 30739231, 2019). "A previous study showed that cPLA2 may play an essential role in pericyte recruitment, demonstrated by the absence of α-SMA- and desmin-positive pericytes around tumor vasculature in cPLA2-deficient mice." (PMID 26951085, 2016). "Thus, the increase of perivascular desmin+/SMA+ cells is specific of irradiated tumor microvessels." (PMID 24391887, 2013).
tumor (continued). "Desmin is a smooth-muscle type intermediate filament protein, expressed by smooth muscle cells, but also found expressed in fibrotic tissue in wound healing and in tumor 'desmoplastic' stroma, yet the origin of the cell type expressing desmin has been controversial." (PMID 22141345, 2011). "We tested this hypothesis by staining the tumor vasculature with an endothelial marker (Meca-32) and a mature pericyte marker (Desmin) to determine the relative pericytic coverage of the tumor vasculature comparing control tumors, erlotinib-treated tumors, and Hb-egf mutant tumors." (PMID 20975924, 2010). "INI-1 was retained in the tumor cells, and WT1, desmin, myogenin, BCOR, TLE-1, CD45CLA, and synaptophysin were all negative (not shown)." (PMID 41230381, 2026). "Immunohistochemical staining demonstrated that the tumor cells were positive for CD34, desmin, androgen receptor, and progesterone receptor." (PMID 41529035, 2026). "A small minority of tumor cells were convincingly positive for HMB45, and rare cells stained with SALL4, CD117, glypican‐3, myogenin, desmin, and synaptophysin." (PMID 40610013, 2026). "Immunohistochemically, the tumor cells are positive for SMA and MSA, with occasional desmin expression." (PMID 40282503, 2025). "Immunohistochemistry revealed that tumor cells were positive for SMA (43/43), Desmin (42/43), and Caldesmon (40/43)." (PMID 40276735, 2025). "Immunohistochemistry revealed that a few tumor cells exhibited focal nuclear positivity for β-catenin, focal positivity for SMA, and desmin positivity, as well as CD34 positivity in vessels, whereas they remained negative for CD117 and S-100 in tumor cells." (PMID 41181483, 2025). "Immunohistochemistry results were as follows: CD117 (+), CD34 (+), Desmin (-), DOG-1 (+), Ki67 positivity in approximately 5% of tumor cells, S-100 (-), SDHB (+), SMA (few cells +), SOX-10 (-)." (PMID 40365338, 2025). "Immunohistochemical (IHC) staining for SMA, desmin (DES), and caldesmon (CALD1) resulted positive, demonstrating the smooth muscle lineage of the tumor, whereas CD34 highlighted only the vascular component." (PMID 39051589, 2025). "Immunohistochemical (IHC) staining further confirmed the tumor's smooth muscle and mesenchymal origins, with positive for Vimentin, SMA, Syn, Actin, Desmin, and CD34." (PMID 39776317, 2025). "Immunohistochemical profiling showed CD117 (+), CD34 (+), Desmin (-), DOG-1 (+), Ki67 (approximately 5% positive tumor cells), S-100 (-), SDHB (+), SMA (a few cells +), and SOX-10 (-)." (PMID 40365338, 2025). "Immunohistochemically, the tumor cells are positive for smooth muscle actin (SMA) in almost all cases and desmin in more than half of them." (PMID 40002892, 2025). "Histopathology classified the tumor as the solid subtype of ALM, showing interlacing bundles of smooth muscle cells surrounding vascular channels, with smooth muscle actin and desmin positivity and S-100 negativity." (PMID 41465909, 2025). "The myofibroblastic nature of the tumor is highlighted by the immunohistochemical positivity of the neoplastic cells for smooth muscle actin (SMA), with varying degrees of desmin, calponin, and CD34 positivity." (PMID 41255404, 2025). "Given that ASPLT is defined by a certain immunophenotype - CD34 and desmin positivity with Rb protein loss - the absence of IHC data raises concerns about the reliability of these diagnoses and limits their value in refining our understanding of the tumor’s defining features." (PMID 41527615, 2025). "Immunohistochemical examination identifies specific tumor cell markers, such as Vimentin, SMA, Desmin, etc., which assist in determining the tumor type and origin." (PMID 40746595, 2025).